AKT1 (AKT serine/threonine kinase 1)
Diseases named in the same sentence as AKT1 in open-access papers (continued):
Sharing a sentence is not in itself a finding about the gene and the disease.
schizophrenia (continued). "Also a number of post-mortem studies show evidence of a decrease in AKT1 expression in brains of individuals with schizophrenia." (PMID 22393424, 2012). "We hypothesized that if this is indeed the case, we should observe both decreased AKT1 expression as well as deregulation of AKT1 regulated pathways in Peripheral Blood Mononuclear Cells (PBMCs) of schizophrenia patients." (PMID 22393424, 2012). "Although we could not investigate gene-environment interaction because of the lack of data, our finding indirectly implicates a possible role for the AKT1 gene in obstetric complications and schizophrenia." (PMID 20046382, 2009). "Finally, our adhesion studies and findings have brought at least three promising schizophrenia susceptibility genes–NRG1, COMT, and Akt1–together in a coherent, biologically plausible framework." (PMID 18159252, 2007). "Indeed, AKT1 protein levels were found to be significantly reduced in lymphocyte-derived cell lines and in the frontal cortex and hippocampus of postmortem brains of schizophrenia patients compared to controls." (PMID 36979877, 2023). "Thus, future studies of epistatic interactions between genes such as COMT and AKT1 might help in elucidating the relationship between schizophrenia and cancer that has been discussed in epidemiological studies." (PMID 20520724, 2010). "Accumulating evidence implies that both AKT1 and GABAA receptor (GABAAR) subunit genes are involved in schizophrenia pathogenesis." (PMID 27615800, 2016). "Accumulating evidence indicated that AKT1 and NRG1 were involved in social functions of schizophrenia." (PMID 25688191, 2014). "In this study we show decreased expression of AKT1 in PBMC's of young, recent-onset, male schizophrenia patients." (PMID 22393424, 2012). "Accumulating evidence suggests AKT1 and DRD2-AKT-GSK3 signaling involvement in schizophrenia." (PMID 31959776, 2020). "CACNA1C41,42, GRIN2A43 (interacted with elite gene AKT1), TNF44, and aberrant SRR45 may contribute to schizophrenia pathogenesis." (PMID 30705251, 2019). "More specifically, AKT1 is a downstream mediator of the PI3K pathway that regulates synaptic formation and plasticity and which imbalance leads to autism and schizophrenia; genetic variations in contactins (CNTN) have been described in association with neurodevelopmental disorders, including autism." (PMID 28993790, 2017). "The protein-protein interaction map of genes regulated by one of the two top microRNAs shows that GABBR1 and AKT1 are both hub proteins, forming a plausible network of interacting proteins, comprising several key players in the GABA and signaling pathways in schizophrenia." (PMID 26450699, 2015). "AKT1, protein kinase B is an important molecule in signaling pathways and is known to be downregulated in recent-onset schizophrenia although the source of this downregulation is not known." (PMID 26450699, 2015). "For example, studies of schizophrenia have revealed synergistic SNP-SNP interactions in dopamine receptor D4 (DRD4) and in neuregulin 1 (NRG1)/v-erb-a erythroblastic leukemia viral oncogene homolog 4 (avian) (ERBB4)/AKT1 genes." (PMID 24955105, 2014). "We extend their findings by showing that AKT1 is also decreased in non-cultured PBMC's of schizophrenia patients, collected in a clinical setting, and that decreased expression is also observed in medication-free or -naive patients." (PMID 22393424, 2012). "Despite the overlap of COMT and AKT1 in associations with cancer and schizophrenia, molecular and cell biological interactions of COMT and AKT1 have not been explored." (PMID 20520724, 2010).
schizophrenia (continued). "They found significant evidence for a gene x environment interaction in V-akt murine thymoma viral oncogene homolog 1 (AKT1), brain-derived neurotrophic factor (BDNF), dystrobrevin binding protein 1 (DTNBP1), and glutamate receptor metabotrophic (GRM) genes in developing schizophrenia." (PMID 20046382, 2009). "Indeed, the β-arrestin-2/AKT1/GSK-3 pathway has been found to be affected under conditions of D2R hyperstimulation, as those hypothesized in schizophrenia." (PMID 36979877, 2023). "Therefore, AKT1 hypoactivity and GSK-3 hyperactivity may represent postsynaptic mechanisms of heightened D2R-mediated dopaminergic tone, as is supposed to occur in schizophrenia." (PMID 36979877, 2023). "However, to date, while the majority of studies related to schizophrenia have focused on AKT1, particularly in the prefrontal cortex and hippocampus, this does not exclude the possible role of other AKT isoforms in the pathophysiology of schizophrenia." (PMID 35625659, 2022). "Secondly, the expression level of DRD2, PI3KCB, and AKT1 in peripheral blood may not an index of schizophrenia, but only an index of psychiatric symptoms." (PMID 29156812, 2017). "Notably, antipsychotic treatments significantly increased AKT1 and GSK-3 phosphorylation in the rodent brain, possibly indicating that antipsychotics may revert the putative alterations in these two molecules in schizophrenia patients." (PMID 36979877, 2023). "Consistent with the ARRB2/PP2A complex formation, the ARRB2/PP2A/AKT1/GSK3 signal pathway facilitates the dephosphorylation and deactivation of AKT, resulting in the activation of GSK3, and may be an attractive potential factor in the DA hypothesis of schizophrenia." (PMID 35062349, 2022).
thyroid cancer (113 papers, 2012 to 2025). "An AKT1 (G49A) mutation has been seen in thyroid cancer metastasis, suggesting that this mutation arises late during progression." (PMID 32751138, 2020). "Mutations in PIK3CA, AKT1, and PTEN have been associated with aggressive, radioactive iodine-refractory thyroid tumors and are typically late events in thyroid cancer pathogenesis." (PMID 40149275, 2025). "Normal thyroid expresses all three isoforms of AKT (AKT1, AKT2, and AKT3), and AKT plays a crucial role in the development and progression of thyroid cancer." (PMID 41157173, 2025). "Mutations in the PI3K/AKT/mTOR pathway, including PIK3CA, AKT1 and PTEN are infrequent in thyroid cancer, though they can act as early driver mutations in certain RAS-like subtypes." (PMID 39926346, 2025). "Other genetic mutations reported in various thyroid cancer include RAS PIK3CA, AKT1, PTEN, mTOR, and chromosomal rearrangements involving RET/PTC and PAX8-PPARɣ genes." (PMID 39724083, 2024). "It is worth noting that thyroid cancer patients with mutations in PIK3CA or AKT1 almost always also have BRAF mutations, indicating an interaction between the RAS/BRAF/MAPK pathway and the PI3K/AKT pathway in driving thyroid cancer development." (PMID 38313845, 2023). "While all three Akt isoforms regulate thyroid growth, Akt1 is the primary promoter of thyroid cancer development and local invasion, while vascular invasion and metastatic progression are dependent on Akt1 and 3, and to a lesser extent Akt2." (PMID 33110146, 2020). "Somatic single nucleotide variants (SSNVs) of AKT1, AKT2, and AKT3 have been detected in thyroid cancer at a very low frequency." (PMID 32751138, 2020). "Consistently, AXL stimulation with its ligand growth arrest-specific gene 6 (GAS6) increased AKT1- and p65 NF-kB-phosphorylation and promoted survival of thyroid cancer cell lines in culture." (PMID 31181609, 2019). "This alteration in AKT1 occurs in about 15% of metastatic thyroid cancers, while also occurring in small fractions of ATCs and FTCs." (PMID 28117295, 2017). "Thyroid cancer may also be triggered by an overactive phosphatidylinositol-3 kinase (PI3K/AKT) pathway due to activating mutations in RAS, PIK3CA, or AKT1, or inactivation of PTEN." (PMID 35659616, 2022). "Taken together, these data confirmed the central role of Akt1 in thyroid cancer induction and progression, identified a new role for Akt 2 and 3 in metastasis and uncovered a potential new Akt1-mediated DC suppression pathway in thyroid cancer progression in this model system." (PMID 33110146, 2020). "In another study, the integrative analysis of aggressive thyroid carcinomas, including ATC and advanced DTC, revealed the frequent presence of TERT, AKT1, PIK3CA, and EIF1AX mutations in combination with BRAFV600E and RAS mutations in these advanced forms of thyroid cancers." (PMID 32751138, 2020). "The Akt1 and Akt2 isoforms are clearly expressed and activated in thyroid cancer." (PMID 31109060, 2019). "It is the overexpression and overactivation of AKT1, rather than mutation of the AKT1 gene, that contributes to the pathogenesis of sporadic thyroid cancers, particularly in follicular thyroid cancers (FTC)." (PMID 28117295, 2017). "Thus, Akt1 is critical for cancer induction and metastasis in this model of thyroid cancer." (PMID 33110146, 2020). "These xenograft animals include xenografted BALB/c mouse models of PTC (HEMGN, AKT1), TNBC (AKT1), OC (PLXNB2), thyroid gland carcinoma (TC) (KLK4), and xenografted nude mouse models of GBM (HMGA1) and CHOL (LY6E)." (PMID 36175921, 2022). "As in AKT1, genetic alterations in PIK3CA appear late during malignant progression of thyroid cancer and are more common in ATC than DTC." (PMID 32751138, 2020).
thyroid cancer (continued). "We previously reported that depletion of Akt1 delayed thyroid tumor development and inhibited lung metastasis in the PVPV mouse thyroid cancer model." (PMID 33110146, 2020). "miR-451a is one of the most downregulated miRNAs in thyroid cancer, and reduces the protein levels of its recognized targets MIF, AKT1, and c-MYC in PTC cell lines, attenuating AKT pathway activation." (PMID 31312183, 2019). "For example, depletion of INPP4B selectively activates AKT2 but not AKT1 in the endosomes of thyroid cancer cells." (PMID 30012111, 2018). "On this basis, the authors proposed that either Akt2 or Akt3 might be activated in thyroid cancers rather than Akt1." (PMID 26793165, 2015).
depression (109 papers, 2012 to 2026). "For instance, the SNPs rs1130214 and rs3730358 have been associated with higher Akt1 level, bipolar disorder, and major depression." (PMID 35525984, 2022). "The associations between the 17-item Hamilton Depression Rating Scale, total score, four factors, and the Akt1 rs2494746 and rs3001371 polymorphisms were analyzed through UNPHASED software." (PMID 35855329, 2022). "It seemed that Akt1 polymorphisms are connected with anxiety symptoms in patients suffering from depressive disorder." (PMID 35855329, 2022). "AKT1 polymorphisms are associated with depression severity, anxiety symptoms and suicide attempts in patients with depressive disorder." (PMID 34051074, 2021). "Protein products of MTOR and TSC2 are implicated via their connections with AKT1 in regulation of synaptic plasticity and memory; these are impaired in depression, possibly as a result of a reduction of hippocampal volumes." (PMID 33193575, 2020). "Other top associated probes were located in gene bodies of MAD1L1 (p-value = 5.16 × 10−6), SLC29A2 (p-value = 6.15 × 10−6) and AKT1 (p-value = 4.47 × 10−6), all genes associated before with development of depression." (PMID 31477683, 2019). "AKT1, a serine/threonine kinase central to critical biological processes such as cell survival, proliferation, metabolism, and growth, has been implicated in the pathophysiology of major depressive disorder (MDD)." (PMID 40699741, 2025). "In the central nervous system, the inhibition of AKT1 may cause increased neuronal apoptosis and lead to depression." (PMID 39408591, 2024). "Additionally, there was a significant correlation between the severity of depression and the AKT1 gene polymorphisms." (PMID 36560929, 2022). "AKT1 has attracted much attention in the study of depression, and it is associated with depression, anxiety symptoms, work, activity, and suicidal tendency of patients with depression." (PMID 34479552, 2021). "AKT1 gene polymorphisms may be a sign of depression severity and treatment response." (PMID 34976096, 2021). "Topological analysis of the bioactive-target-pathway network indicated that MAPK1, PIK3R1, EGFR, AKT1, and SRC were the core targets enriched in crucial signaling pathways associated with treating depression by A. laxiflora." (PMID 38505421, 2024). "This indicated that baicalin mitigates depression and alleviates the altered behavior and hippocampal inflammation by targeting the Akt1 pathway through the modulation of gut microbiota composition and metabolites." (PMID 37764277, 2023). "According to STRING 11.0 protein interactions, the network of 69 targets related to the treatment of depression by KXS was extensively connected with AKT1 as the core." (PMID 35911169, 2022). "We identified depression-associated targets of KXS compounds, among them AKT1 was identified as core antidepressive target of KXS." (PMID 35911169, 2022). "One theory was that AKT1 was closely related to bipolar disorder (BD), a mental genetic disease characterized by depression and mania." (PMID 36560929, 2022). "Although a recent cohort study contradicted the relationship between AKT1 and BD, the correlation with the occurrence of depression was certain." (PMID 36560929, 2022). "A reduction in the kinase activity of AKT1 is related to depression." (PMID 34976096, 2021).
depression (continued). "Moreover, the binding of NTRK2 and BDNF activates the PIK3CA/AKT1 pathway, which promotes synaptic plasticity and enhances long-term potentiation to alleviate depression." (PMID 33935736, 2021). "The PIK3CA/AKT1 pathway is a core component in the pathogenesis of depression." (PMID 33935736, 2021). "For instance, AKT1 is involved in myelination of the peripheral nervous system, peripheral nervous system axon ensheathment, and the neurotrophin signaling pathway, all of which are closely related to depression." (PMID 32256358, 2020). "Molecular docking analysis results exhibited that core targets of depression, such as SRC, EGFR, PIK3R1, AKT1, and MAPK1, bind stably with the analyzed bioactive compounds of A. laxiflora." (PMID 38505421, 2024). "Among the top 10 hub gene targets, MAPK1, AKT1, PIK3R1, EGFR, STAT3, and SRC were the most enriched targets in the selected KEGG pathway, suggesting their critical role in the pathogenesis of depression." (PMID 38505421, 2024). "The data suggested that MAPK1, EGFR, and AKT1 were the major protein targets for achieving the desired pharmacological effect, whereas, quercetin and 3-acetylursolic acid might be predicted as the most active phytoligands of A. laxiflora to treat mental depression." (PMID 38505421, 2024). "Baicalin inhibits microglia activation by regulating the NLRP3, AKT1, and S1RT1-NF-κB signaling pathways and consequently alleviates neuroinflammation and depression." (PMID 37764277, 2023). "Based on the network topology combined with the PPI analysis, we obtained that TCEF can regulate depression through five core targets, namely, ALB, AKT1, TNF, ESR1, and CTNNB1." (PMID 36506595, 2022). "It was verified that HSP90AA1 was up-regulated in patients with depression, which correlated with elevated levels of VEGF, VEGFR2, PI3K, and AKT1." (PMID 36045654, 2022). "UHPLC-Q-EOMS was employed to identify 59 major components of TCEF, and network pharmacology analysis was used to screen 48 active components of TCEF for treating depression, corresponding to 139 relevant targets, including ALB, AKT1, TNF, ESR1, and CTNNB1." (PMID 36506595, 2022). "Studies have shown that AKT1, VEGFA, ESR1, IL6, and AR play an important role in the treatment of depression." (PMID 34257681, 2021). "Luteoklin, quercetin, kaempferol and other active compounds in Epicedium can regulate multiple signaling pathways and targets such as IL6, AKT1, and EGF, therefore playing therapeutic roles in depression." (PMID 34479552, 2021). "The target-pathway network illustrated that AKT1, MAPK1, GSK3B, TNF, MTOR, and PTEN were core targets enriched in key signaling pathways that played crucial roles in the treatment of depression by CCHP." (PMID 34976096, 2021). "Overall, our study verified that during states of excessive oxidative stress, the PIK3CA/AKT1/NFE2L2/KEAP1 and PIK3CA/AKT1/BDNF/NTRK2 signaling pathways are suppressed, which induced OB rats to exhibit phenotypic behaviors of depression." (PMID 33935736, 2021). "There are three subtypes of AKT (AKT1, AKT2, and AKT3), and AKT1 is the most important subtype, which plays an important role in depression." (PMID 34257681, 2021). "In PPIN, the main hubs such as AKT1, JUN, MAPK8 and STAT3 have already been reported to be involved in depression." (PMID 28954415, 2017). "PPI network analysis identified core targets such as MAPK3, STAT3, AKT1, PRKACA, MAPK1, and TNF, suggesting BCBL's efficacy in depression treatment may stem from its action on multiple key targets." (PMID 40909251, 2025).
depression (continued). "Akt1, an important downstream substrate in the phosphatidylinositol 3-kinase (PI3K) pathway, is involved in nociceptive information processing, anxiety and depression-like behaviours." (PMID 35098831, 2022). "The key targets of Epicedium for treating depression were IL6, VEGFA, AKT1, and EGF." (PMID 34479552, 2021). "In conclusion, we have performed EWAS of depression symptomatology score in a unique cohort of elderly monozygotic twins and identified blood methylation levels at KLK8, DAZAP2, MAD1L1, SLC29A2, AKT1, and other genes, as well as several DMRs across the genome to be associated with this trait." (PMID 31477683, 2019). "Notably, hub genes such as Nrf2, AKT1, and PIK3CA are involved in key processes critical for neuronal survival, synaptic plasticity, and mood regulation, indicating their potential role in both the onset and progression of depressive disorders." (PMID 40290092, 2025). "Therefore, we speculate that JTW may play a role in the treatment of DM and depression through the key targets such as INS, AKT1, IL-6, VEGF-A, TNF and so on." (PMID 34875999, 2021).